CXCL8 (C-X-C motif chemokine ligand 8)
Diseases named in the same sentence as CXCL8 in open-access papers (continued):
Sharing a sentence is not in itself a finding about the gene and the disease.
tumor (continued). "It has been shown that the genes encoding chemokines CCL20, CXCL8/IL-8, and the adhesion molecule L-selectin are overexpressed in PTC in comparison to normal thyroid, independently from the RET/PTC or BRAF status, suggesting that these chemokines could be associated with tumor-related inflammation." (PMID 31500315, 2019). "In cancer cells, CXCL8 and vascular endothelial growth factor (VEGF) cooperate to establish and expand tumor neovascularization." (PMID 31788042, 2019). "Similar results were obtained for the OSCC and OAC subgroups, where the AUC of CXCL-8 was also lower than that of CRP and higher than those of the classical tumor markers." (PMID 30820705, 2019). "In our previous study concerning the measurement of concentrations of a specific receptor for CXCL-8 (CXCR-2), we found statistically significant differences only between serum CXCR-2 levels and tumor differentiation (G factor)." (PMID 30820705, 2019). "Cytokine analysis in tumor patients revealed comparatively lower levels in IL-16, IL-18, CXCL8 (IL-8), IL-9, and CXCL10 (IP-10), indicating that the higher T cell numbers were not accompanied by increased T cell activity." (PMID 30740106, 2019). "These are not only the tumor cells which participate in TAN recruitment, but others like TAM and T-regulatory lymphocytes, the latter acting through CXCL8." (PMID 30680411, 2019). "Alyssa D. Gregory and A. Mc Garry Houghton suggest two different possible strategies: (a) targeting the “CXCL-8/CXCR-1/CXCR-2 axis,” thereby entirely exhausting TANs or (b) targeting specific PMN-derived substances able to induce tumor growing." (PMID 31799175, 2019). "Interleukin-8 (IL-8), also known as CXCL8, which is secreted by tumor and inflammatory cells, promotes tumor migration, invasion, angiogenesis, and metastasis by binding with its receptors, CXCR1 and CXCR2." (PMID 31684995, 2019). "For example, tumor cells, macrophages, and neutrophils produce CXCL1, CXCL2, CXCL5, and CXCL8 and these chemokines recruit MDSCs, both the PMN-MDSCs and the Monocytic-MDSCs." (PMID 30873179, 2019). "We revealed that in the total OC group, the AUC of CXCL-8 was lower than that of CRP, but higher in comparison with the AUCs of the classical tumor markers in OC diagnosis." (PMID 30820705, 2019). "The elevations in CXCL8 and CCL2 expression partly depended on direct physical contacts between the tumor cells and the MSCs/CAFs, whereas CCL5 up-regulation was entirely dependent on cell-to-cell contacts." (PMID 31031757, 2019). "And they can modify TME that subsequently leads to tumour cell proliferation by producing proangiogenic factors (CXC12, VEGF, FGF, IL8/CXCL8, and PDGF-C), CCL-2, IL-6, FAP, IL-4, hyaluronan, IL-8, CXCL9, CXCL10, CXCL12, and Fsp1." (PMID 30944831, 2019). "Moreover, our findings indicated that when tumor cells interacted with stromal cells in the presence of pro-inflammatory stimuli, TNFα-induced p65 activation has led to elevated Notch1 expression and activation, which then gave rise to elevated production of CXCL8." (PMID 31105691, 2019). "The highest diagnostic sensitivity was obtained for the combined measurement of CXCL-8 and CRP (100%), and this value was higher than that for the combined measurement of the classical tumor markers (76%)." (PMID 30820705, 2019). "Mechanistically, DLBCL can produce C-X-C motif chemokine ligand 8 (CXCL8), which can recruit neutrophils expressing APRIL, thereby providing the tumor cells with pro-survival signals." (PMID 30881917, 2019). "CXCL8 is capable of inducing tumor stemness and maintaining, via an autocrine loop, the epithelial to mesenchymal (EMT) phenotype transition of tumor cells." (PMID 30870978, 2019). "In return, TAMs facilitate tumor progression by providing supporting factors such as MMPs, cathepsins, VEGF, PDGF, FGF and various chemokines like CXCL8 that assist tumors to proliferate, invade and metastasize." (PMID 30925924, 2019).
tumor (continued). "Chemotactic cytokines released from a tumor microenvironment i.e. CCL2, CXCL1, CXCL10, PGE2, histamine, VEGF, angiopoietin 1 (Ang1), CXCL8/IL-8 attract mast cells from the vicinity and recruit them from circulation." (PMID 30680411, 2019). "M-MDSC were shown to accumulate in tumor via CCL2-dependent mechanisms, whereas PMN-MDSC accumulate in a CXCL8-depenent manner." (PMID 30936876, 2019). "Apart from CCL2, there are certain other chemokine attractants exuded by the tumor mass such as CCL5, CXCL8, CCL7 and CXCL12 and a few other cytokines like VEGF and M-CSF." (PMID 30925924, 2019). "For instance, RET/PTC induces the expression of oncogenes involved in inflammation and tumor invasion, such as chemokines (CCL2, CCL20, CXCL8/IL-8, and CXCL12), chemokine receptor CXCR4, and cytokines (IL-1B, colony-stimulating factor 1, and GM-CSF)." (PMID 31500315, 2019). "The cytokines IL-8/CXCL8 and IL-6 are both upregulated in many tumors and well-known to promote tumor progression." (PMID 31661927, 2019). "MDSCs are attracted to tumor sites in response to various cytokines (CCL2, CCL5, and CSF1 for M-MDSCs, and CXCL1, CXCL5, CXCL6, CXCL8, and CXCL12 for PMN-MDSCs)." (PMID 31412566, 2019). "Concurrent inhibition of IL-6 and CXCL8 expression in TNBC cells inhibits colony formation, cell survival, and tumor growth." (PMID 30034618, 2018). "Diverse chemokines, i.e., CCL2 (MCP-1), CCL5 (RANTES), CCL7 (MCP-3), CXCL8 (IL-8), and CXCL12 (SDF1), released by tumor cells induce migration, differentiation, and survival of tumor-infiltrating myeloid cells." (PMID 29686671, 2018). "CXCL8/IL-8 retains a well-known chemotactic activity for neutrophils, acting through CXCR1/2 and playing a pivotal role in the tumor microenvironment (TME)." (PMID 29953504, 2018). "Recently, furthermore IκB kinase-dependent expression of proinflammatory chemokines such as IL-8 or CXCL8 have been detected that enhance, in addition to induction of apoptosis, proliferation of tumor cells." (PMID 30544838, 2018). "A significantly stronger induction of CXCL8 and CCL2 was observed in our tested tumor cells as compared to HEK." (PMID 30266096, 2018). "Comparison between the primary tumor myeloid lineage cells and the metastatic myeloid lineage cells showed elevated levels of CC2, CC3, CC4, CXCL8 and TNF in the primary tumor." (PMID 30383866, 2018). "However, the exact mechanism underlying CXCL8 overexpression in tumor cells is not well defined." (PMID 29636079, 2018). "All tumor cell lines, but UD-SCC 7A, showed significantly higher expression levels of CXCL8 compared to HEK for most of the used concentrations." (PMID 30266096, 2018). "In the present study, we measured in tumor tissue the quantity of the angiogenic chemokines CXCL6 and CXCL8 (IL-8) and the most widely studied angiogenic factor VEGF along with the angiostatic chemokine CXCL4." (PMID 29850390, 2018). "Similar to MDSCs, TAMs and TANs are recruited to tumor sites by tumor-derived chemokines and growth factors, including CCL2/MCP-1, CXCL1/Gro-a, CCL7/MCP-3, CCL5/RANTES, CXCL8/IL-8, VEGF, PDGF, and M-CSF/CSF-1." (PMID 29735917, 2018). "In genetically modified mice that expressed human CXCL8, MDSC were efficiently recruited to the tumor site and suppressed T cell activity." (PMID 30319622, 2018). "Interleukin-8 (IL-8, CXCL8) is a pro-inflammatory and pro-angiogenic chemokine that stimulates cancer progression by inducing tumor cell proliferation, survival, and migration." (PMID 30089134, 2018). "Neutrophils are recruited at the tumor sites by several chemokine signals, such as CXCL12, CXCL8, CCL3 (MIP-1α), and CXCL6 (huGCP-2), or murine chemokines CXCL1, CXCL2, and CXCL5." (PMID 30591657, 2018). "The IL-1α pathway has been implicated in a feed-forward signaling loop that leads to the production of pro-tumorigenic factors that contribute to malignant transformation, tumor formation and production of angiogenic factors, including CXCL1 and CXCL8." (PMID 29502208, 2018).
tumor (continued). "The presence of cytokines in the ACP tumours was also assessed by multiplex ELISA against IL1B, IL6, IL8 (CXCL8), IL10, IL18, TNF (TNFα) and IFNG (IFNγ), which revealed the expression of all of these but IFNG in protein lysates from eight human ACPs." (PMID 29541918, 2018). "Immunohistochemical staining of xenograft tumor tissues was conducted to evaluate the protein abundance of DACH1, cyclin D1, Ki-67, and CXCL8 in DACH1-overexpressed and control tumors." (PMID 29636079, 2018). "In particular, the chemokines CCL2, CCL3, IL-8/CXCL8, and CXCL12 are consistently involved in promoting osteoclastogenesis and tumor growth." (PMID 29930538, 2018). "Previous studies have investigated the angiogenic expression profiles in HNSCC tumour tissues compared to normal tissue and have identified VEGF, IL-8/CXCL8, FGF-2 and HGF as key mediators of angiogenesis in HNSCC patients." (PMID 30001714, 2018). "Inhibition of CXCL8–CXCR1/2 signaling by CXCL8 antibodies, or small molecules targeting CXCR1 and/or CXCR2, also decreases tumor growth and progression in tumor mouse models." (PMID 30304046, 2018). "Our results suggested that increased CXCL8 protein occurred in ADC patients and was significantly correlated with tumor progression and poor prognosis." (PMID 29636079, 2018). "Numerous cytokines, such as CXCL8, IL-6, and CXCL5, trigger inflammatory responses by recruiting and activating relevant inflammation cells in the tumor foci resulting in tumor growth, progression, and immunosuppression." (PMID 29636079, 2018). "In the tumor microenvironment, autocrine CXCL8/IL8 signalling has been ascribed as a mechanism of survival and as a mechanism of proliferation and increased metastatic potential of cancer cells expressing the cognate receptor." (PMID 30126117, 2018). "TAMs play an important role for lymphangiogenesis through the release of VEGF-C and VEGF-D via VEGFR3, and neo angiogenesis by VEGF, TNF-α, CXCL8, PDGF-β, MMP2, MMP7, and MMP9, both of mechanism are critical steps for tumor growth, invasion, and metastasis." (PMID 29963061, 2018). "TNFα evoked release of tumor-promoting chemokines such as CCL2 (MCP-1), CCL5 (RANTES) and CXCL8 (IL-8) trigger infiltration of CCR2/CCR5 receptor bearing leukocyte sub-populations (LSPs) including TAMs, MDSCs, TANs, Tregs, MAMs and CAFs." (PMID 28441391, 2017). "Often released by tumor or macrophages for local suppression of anti-tumor immune responses, including TGF-β, CCL5, CCL7, CXCL8, IDO, etc." (PMID 29299180, 2017). "Inflammatory cytokines, such as IL-6 and CXCL8, are known to support M2 macrophage polarization, whereas TGF-β recruits and retains macrophages at the tumor site and enables effective tumor evasion of the host immune system." (PMID 28052009, 2017). "CAFs also secrete factors including VEGF, CXCL12, FGF, IL-8/CXCL8 and PDGF to stimulate tumor angiogenesis, CAFs release factors such as HGF, CCL5 and stanniocalcin 1 (STC1) to stimulate tumor invasiveness and metastasis." (PMID 29383119, 2017). "It is recruited to the tumour microenvironment by chemokines such as CXCL8,CXCL1,CXCL2, and CXCL3 by the production of inflammatory mediators such as TNF-Alfa, MIP-1 ALFA, H202, and NO that are cytotoxic to tumour cells." (PMID 28275390, 2017). "Among these differentially expressed genes, pro-inflammatory cytokines, such as IL6, CXCL1, CXCL5, CXCL8, and CSF2 were further validated as significantly downregulated in WCE-treated PC-3 and DU145 tumor tissues." (PMID 29142311, 2017). "For example, tumor secrete ligands CCL5, CCL7, and CXCL8, bind to their receptors CCR1 or CXCR2 expressed on subtypes of MDSCs, and attract MDSCs in the tumor microenvironment." (PMID 29299180, 2017). "It is known that interleukin 8 (IL-8 or CXCL8) is secreted from leukocytes, fibroblasts, endothelial cells as well as tumor cells." (PMID 28947965, 2017).
tumor (continued). "CXCL8 can be induced by hypoxia even in HIF-1-deficient CRC cells as a compensatory pathway of VEGF to preserve tumor angiogenesis, suggesting the potential for combination regimens that target both HIF-1 and CXCL8." (PMID 27136535, 2016). "Neutrophil recruitment can also be targeted by blocking CXCL8 or CXCL6 signaling with antibodies, and this approach has produced similar benefits in inhibiting tumor growth and metastasis." (PMID 26997761, 2016). "Chemokines in the omental tumor tissues revealed some changes as follows: 1) the decreased levels in CCL26, CCL28, CXCL1-3, CXCL8 and CXCL16; 2) the increased level in CCL24; and 3) the conserved level in CCL20 compared to the parental cells." (PMID 27723802, 2016). "In a large group of HCC patients, we confirmed that HIF-1α and CXCL8 expression is increased in HCC tissues, compared with adjacent non-tumor liver tissues." (PMID 26078356, 2015). "The chemokine (C-X-C motif) ligand 8 (CXCL8), also known as interleukin-8 (IL-8) increase was time-dependent and coincided with the dynamics of tumor progression." (PMID 26414070, 2015). "TNF-α (and IL-1β) induced the release of CCL2, CXCL8 and CCL5 by MSCs and CAFs generated by prolonged stimulation of MSCs with Tumor CM of MDA-MB-231 and MCF-7 cells." (PMID 25928089, 2015). "We have shown that endothelial cells secrete IL-6, CXCL8, and EGF that induce phosphorylation of STAT3, AKT, and ERK in tumor cells, and that these phosphorylation events enhance tumor cell survival and migration." (PMID 26287605, 2015). "Tumor angiogenesis is a consequence of an imbalance between pro-angiogenic factors, such as the vascular endothelial growth factor (VEGF) family and IL-8/CXCL8, and inhibitors of angiogenesis, including endostatin, angiostatin and other related molecules." (PMID 25947641, 2015). "Recent studies suggest that ErbB2 as well as EGFR can also be trans-activated by cytokines including Interleukin-8 (IL8; CXCL8), a neutrophil chemoattractant and an angiogenic factor with tumor promoting properties." (PMID 26084289, 2015). "We then measured the expression of IL-1 proteins (IL-1α and IL-1β), CXCL8/IL-8, and VEGF family proteins (VEGF-A, -C, and -D) in cancer cells and/or tumor stromal macrophages in lower and highly metastatic tumors." (PMID 24924428, 2014). "CAFs produce CCL2, CCL5, CCL7, CXCL8, and CXCL14 and these chemokines promote tumor progression mainly by enhancing the motility of tumor cells." (PMID 24966464, 2014). "FPR1 selectively expressed by GBM cells when activated by exogenous and tumor derived agonists promotes tumor cells to produce proangiogenic factors VEGF and the angiogenic chemokine CXCL8." (PMID 25110692, 2014). "CXCL8-secreting PC3 cells were co-cultured overnight with either THP-1 or WPMY-1 cells prior to wound scratch assays, allowing signaling between tumor and stromal cells to be established." (PMID 24970800, 2014). "In cervical carcinoma, hypoxia stimulates tumor cells to express high levels of CXCR1/2 and CXCL8 that respond to ligands in the microenvironment by proliferating." (PMID 25110692, 2014). "IL-8 (CXCL8) is a CXC family chemokine that activates multiple signaling pathways, increases proliferation and survival of both endothelial and tumor cells and facilitates the migration of these cell types." (PMID 24220935, 2014). "TAMs and MDSCs contributed to tumor angiogenesis by producing a wide variety of angiogenic factors such as VEGF, TGF-β, CXCL8, platelet-derived growth factor (PDGF), and MMPs such as MMP-2 and MMP-9." (PMID 24966464, 2014). "There is evidence that tumor angiogenesis can be stimulated by tumor cell secreted CXC chemokine ligands CXCL5 and CXCL8, via their common receptor CXCR2." (PMID 23531764, 2013). "Chemokines that contribute to immune infiltration into tumor sites and tumor growth include the growth-related (GRO) family of chemokines (CXCL1, 2 and 3) and CXCL8." (PMID 24224100, 2013).
tumor (continued). "Another study in androgen-independent prostate cancer described a similar role for CXCL-8 induction of MMP-9 in tumor invasion and tumor-induced neovascularization." (PMID 23342280, 2012). "The expression of the CXC (ELR+) family members (CXCL1-3/GROα-γ, CXCL8/IL-8, CXCR1/2) was examined in a series of resected fresh frozen NSCLC tumours." (PMID 21298036, 2011). "We found elevated levels of plasma CXCL8 in PDAC, EC, and CP pre surgery and that CXCL8 decreased after tumor resection." (PMID 20214814, 2010). "Several cytokine mRNAs' (CCL3/MIP-1α, CCL15/MIP-1δ, CXCL1, CXCL5/ENA78, CXCL8/IL8, CXCL9/MIG, CXCL10/IP10) were found to be overexpressed in the tumours while CCL15/MIP-1δ, CXCL5/ENA78 and IL8 mRNAs' were overexpressed in paired normals, as well." (PMID 21092330, 2010). "In accordance to these findings, high levels of several inflammatory factors including CXCL8, COX-2, and IL-6 were detected in PDAC tissues, indicating that the tumor tissue provides the blood with inflammatory factors." (PMID 20976171, 2010). "Like CXCL8 and other members of the ELR+ CXC chemokine family, CXCL6 is a neutrophil chemoattractant that was recently demonstrated to promote tumor growth through its angiogenic effects in human tumors and animal models." (PMID 18578857, 2008). "Some data indicate that chemokines, such as IL-8 (CXCL8), MCP-1 (CCL2), and RANTES (CCL5), not only stimulate migration, but also proliferation of tumor and stromal cells, including endothelial cells." (PMID 18728788, 2008). "Interleukin (IL)-8, a member of the CXC chemokine (CXCL8) and a chemoattractant for neutrophils and lymphocytes, can act multifunctionally to induce tumor growth and metastasis, and IL-8 overexpression can occur through TF-FVIIa stimulation." (PMID 15969748, 2005). "Furthermore, QUE downregulated the expression of key inflammatory factors (IL1β, CXCL8, and MMP9), inhibiting neutrophil activation and infiltration, as well as suppressing tumor growth in CRC." (PMID 41601690, 2026). "A recent review suggested recruitment of ASCs from ppWAT into PCa cells and the TME are precursors to tumor stromal cells and cancer‐associated fibroblasts and a source of IL‐6, TNFα, CXCL1, CXCL5, CXCL8, CXCL12, MCP‐1, and leptin facilitating tumor angiogenesis and cancer cell proliferation." (PMID 41450167, 2026). "Moreover, CXCL8 can influence the TME by modulating the function of various immune cells, potentially contributing to immune evasion and tumor progression." (PMID 40087784, 2025). "Moreover, therapeutic targeting of CXCL8 reduces neutrophil infiltration, suppresses NET formation, and inhibits tumor progression." (PMID 40963602, 2025). "Chemokines like CXCL-8 and CXCL1/2/5 in the tumor microenvironment attract neutrophils to infiltrate late-stage tumors, where they release reactive oxygen species (ROS) to induce DNA damage and secrete vascular endothelial growth factor (VEGF) to accelerate angiogenesis." (PMID 40626716, 2025). "Macrophages are the primary producers of numerous molecules that facilitate tumor angiogenesis, such as VEGFA, CXCL8 (chemokine (C-X-C motif) ligand 8), PlGF (placental growth factor), IL-1β (interleukin-1 beta), IL-6 (interleukin-6), TNF (tumor necrosis factor), MMPs, and cathepsins." (PMID 40940953, 2025). "We used antibodies for CXCL5 and CXCL8, the two most highly expressed in PC MET TNMplot samples, via immunofluorescence to compare expression in untreated and gemcitabine treated samples from primary tumor and liver METs to normal pancreatic tissue samples." (PMID 41228334, 2025). "Interestingly, CRC can produce CXCL8 themselves and increase the levels of CXCR1 and CXCR2, which helps the tumor grow, spread, and form metastases." (PMID 40943634, 2025). "Similarly, tumor cells can secrete chemokines such as CXCL12, VEGF, and CXCL8/IL-8, attracting mast cells into the TME, where they become activated and release cytokines, chemokines, and angiogenic factors, further driving tumor progression." (PMID 40438115, 2025).